APC (APC regulator of Wnt signaling pathway)
Diseases named in the same sentence as APC in open-access papers (continued):
Sharing a sentence is not in itself a finding about the gene and the disease.
cancer (continued). "The overall analysis indicated that the frequency of APC promoter methylation was remarkably higher in BC patients than in cancer-free controls." (PMID 27478702, 2016). "Experimental studies have suggested that APC dysregulation is important in epithelial discohesion, particularly in cancer." (PMID 27427963, 2016). "A range of experimental approaches showed that the full-length and cancer-truncated forms of APC displayed very similar kinetics of movement at the centrosome, consistent with the major targeting sequence being localized to the N-terminal half of the protein." (PMID 27144584, 2016). "Taken together, these results highlight the importance of APC throughout all stages of cancer treatment." (PMID 27898031, 2016). "Numerous APC genetically altered mice have been generated and serve as models for colon adenoma and cancer, but their phenotypes are different from the human disease." (PMID 28010732, 2016). "Overlapping Linear Motifs (OLPs) found in the cancer-associated hub proteins (CPs) MYC, APC and MDM2." (PMID 27218803, 2016). "APC, a multifunctional cancer suppressor gene, is involved in not only Wnt signal pathway to regulate β-catenin degradation, but also regulating cytoskeleton movement, controlling cell cycle and influencing cell migration and division." (PMID 27065015, 2016). "Mutations in the APC gene is a major causative event of CRC in humans and identification of modifier genes that affect cancer outcome in the APCMin/+ model is of clinical interest." (PMID 27487143, 2016). "We selected 38 carcinomas with LOH for the APC gene region of chromosome 5, as determined by amplification of the CA repeat region within the D5S346 loci." (PMID 26970738, 2016). "These included homozygous variants calls in genes related to cancer (BRCA1, APC, MEN1), congenital malformation syndromes (TCOF1), metabolic deficiencies (FBP1, HEXA), and neurological diseases (FUS, MLC1, DMD)." (PMID 26547235, 2015). "First, we targeted the following loci given the initial observation from TCGA: five imprinted domains (PEG3, H19/IGF2, DLK1/GTL2, MEST, GNAS) and four cancer genes (APC, MLL3, MGMT, ELF3)." (PMID 26338779, 2015). "Together, our data indicate that not only the mutant or WT status of Rb but also the expression levels of FZR1 and functional activity of the APC/CFZR1 E3 ligase will determine how cancer cells respond to CDK4/6 inhibitor treatment." (PMID 25562820, 2015). "Further, cancer cells with truncated APC have high levels of phosphorylated βcat, suggesting that the step blocked is after βcat phosphorylation." (PMID 26393419, 2015). "β-catenin and other proteins including axin and adenomatous polyposis coli (APC) in the Wnt signaling pathway play an important role in many types of human cancers, including pancreatic cancer." (PMID 25869100, 2015). "Recently, it has also been shown that NTR1 gene is a target of the Wnt/APC oncogenic pathways connected with the β-catenin/Tcf transcriptional complex and NT can stimulate cancer proliferation in an EGFR-dependent mechanism." (PMID 26215716, 2015). "Our results indicate that the level of APC/CFZR1 activity is an important contributing factor in response of cancer cells to CDK4/6 inhibitor treatment." (PMID 25562820, 2015).
cancer (continued). "Among the genes with rare variants in the most individuals are BRCA1, BRCA2, APC, MLL2, and MLL3, genes which are commonly mutated in cancers." (PMID 24728327, 2014). "In our results, the sample with mutant cancer genes APC and KRAS, yielded an inferred probability of 0.95 for the order APC→KRAS, which was consistent with previous studies." (PMID 24586626, 2014). "Cell apoptosis was restored by reconstituting the expression of full-length APC, implicating mutant APC as a determinant of cancer cell resistance to 5-FU." (PMID 25301724, 2014). "Activation of the Wnt/Wg signaling pathway by a mutation in the gene APC is the most common trigger for CRC, inducing benign lesions that progress to carcinomas due to the accumulation of other genetic alterations." (PMID 24516653, 2014). "The purification of APC proteins provides the basis for detailed structure/function analyses of full-length, cancer-truncated and endogenous forms of the protein." (PMID 24156781, 2013). "As these antibodies have been shown to recognise specifically endogenous, native APC, they will also be useful for the study of APC in cells and tissue samples, and for the isolation of APC-containing protein complexes in normal and cancer cells." (PMID 24156781, 2013). "Studies on various cancers provide further support for the idea that expression of APC is affected by promoter methylation." (PMID 24224156, 2013). "The first group of genes displayed higher methylation levels in cancer tissues than in total blood DNA (p16, APC, 3OST2, DAPK1)." (PMID 22629410, 2012). "In total, 1,009 genes were prone to hypermethylation by this analysis in at least one type of cancer, including a number reported to be frequently hypermethylated in cancer (for example, APC, DAPK1, ESR1, GSTP1, SFRP genes and HOX genes)." (PMID 23034185, 2012). "Common regulatory variation affecting the expression of APC and TGFBR1 has also been shown to contribute to susceptibility to cancer in humans." (PMID 22513257, 2012). "Mutations in the Adenomatous polyposis coli (APC) gene are responsible for familial adenomatous polyposis (FAP) syndrome, and are usually an initial event in sporadic cancer development." (PMID 22876303, 2012). "In summary, these studies indicate that the frequently detected large deletions in APC exons are unlikely artifacts of our sequencing analysis, but are most likely cancer-related somatic changes instead." (PMID 23251390, 2012). "A relationship between methylation of CpG sites of APC gene and different types of cancer have recently been observed." (PMID 22414247, 2011). "In light of these results, we decided to revisit previous tests of Axin function in APC mutant cancer cells (typically done in SW480 cells)." (PMID 22645652, 2011). "The simulations also show that an APC+/− stem cell gets selective advantages for dominating the crypt and progressing to cancer." (PMID 21857949, 2011).
cancer (continued). "Further work investigating Cdc42 interaction with APC and its mutants on SW480 cells will likely reveal novel insights into the biology and cancer-causing abilities of these proteins." (PMID 21311754, 2011). "It has been shown that reintroduction of the wild-type APC gene into cancer cells generally reduces tumorigenicity or induces apoptosis." (PMID 21909382, 2011). "For these mutations, we demonstrated that aminoglycoside or negamycin treatment led to a recovery of the biological activity of APC in cancer cell lines, and showed that the level of APC activity was proportional to the level of induced readthrough." (PMID 21909382, 2011). "Reintroduction of the WT APC gene into cancer cells generally reduces tumorigenicity or induces apoptosis." (PMID 21909382, 2011). "DNA methylation and histone modification emerge to work together to silence the expression of a number of genes in cancer, such as APC and hMLH1." (PMID 22414247, 2011). "We analysed cdc14A, that regulates centrosome separation and activates the anaphase promoting complex cdh1/APC, Ndc80/Hec1 (Highly Expressed in Cancer;) a component of APC and Aurora Kinase B, a key regulator of chromosome segregation." (PMID 21187932, 2010). "This is consistent with literature reports that APC is altered in a vast majority of the human sporadic CRCs, and reveals the heterogeneity of sporadic human cancers." (PMID 20707908, 2010). "Genes for which methylation ratios most correlated in normal tissues from cancer patients (N = 56) were RARβ2 and APC (r = 0.502, P < 0.001) and RASSF1A and HIN-1 (r = 0.485, P < 0.001)." (PMID 20226036, 2010). "Mutations downstream of Wnt receptors, such as those found in APC or β-catenin,were the first examples of aberrant Wnt signaling in human cancers." (PMID 21317452, 2010). "This would speed up the mutation or inactivation of the second copy of the APC gene and increase fitness of the APC-carrying cells in the micro-evolution process of cancer progression." (PMID 20406446, 2010). "Hypermethylation of the APC promoter 1A has been demonstrated in e.g. cancer of the colorectum, breast and lung." (PMID 20208994, 2010). "When methylation at the APC gene was considered together with methylation of GSTpi, the sensitivity for detecting cancer approached 100%." (PMID 19002169, 2009). "Examples include members of the MAPK signaling pathway, such as NRAS, a known oncogene; and members of the WNT signaling pathway, DVL2, DVL3, APC and TCF7 which have been previously implicated in colorectal and other cancers." (PMID 19997598, 2009). "Of note, miR-135a and miR-135b were also found to be upregulated in vivo in colorectal adenomas and carcinomas and correlated with low APC levels." (PMID 19912656, 2009). "Inactivation of the adenomatous polyposis coli (APC) gene is a major initiating event in colorectal carcinogenesis occurring in more than 60% of colorectal adenomas and carcinomas and leading to stimulation of the Wnt pathway via free β-catenin." (PMID 19912656, 2009). "The combined use of APC and E-cadherin methylation markers identified a subgroup of cancer patients with worse prognosis (median survival 3.3 vs 16.1 months, P=0.006)." (PMID 15942635, 2005). "With the combined use of the four methylation markers that exhibited differential methylation in cancer (APC, E-cadherin, hMLH1 and TIMP3), 33 (55%) patients had methylated serum DNA detected in at least one of these markers." (PMID 15942635, 2005). "Hypermethylation frequencies for GSTP1, RARB2, RASSF1A, and APC in carcinoma tissues were each >70%, strongly correlating with each other (P<10−6)." (PMID 15292941, 2004).
cancer (continued). "Similar to how APC11 depletion promotes cancer metastasis by inhibiting CRL5 activity and leading to the accumulation of integrin β1, CUL5 knockdown destabilizes APC11, thereby impairing APC/C‐associated processes." (PMID 41159544, 2026). "This may be attributed to the higher penetrance of APC mutations and the earlier onset age of FAP compared to cancers associated with BRCA2." (PMID 39985003, 2025). "We crossed a floxed Itga3 allele into the KPC:APC model to generate KPC:APC:α3flx/flx mice, in which tamoxifen treatment (see Section 2) causes the Cre-mediated deletion of α3 simultaneously with the activation of the cancer-causing genetic lesions." (PMID 39941740, 2025). "Other “Tier 1” cancer-related gene mutations in the COSMIC Cancer Gene Census21 present in the 15 most frequently mutated genes include PIK3R1 (4%), NF1 (4%), NOTCH1 (4%), APC (3%), and ATR (3%)." (PMID 40057511, 2025). "Therefore, a custom target enrichment panel encompassing exonic regions of 303 cancer-related genes was used for enrichment of cDNA and resulted in a coverage of ~300x of the region of interest in the APC gene (total coverage 35 Mio reads)." (PMID 40180948, 2025). "To evaluate the effectiveness of this approach, we analyzed isolated tumor-derived cancer cells (iCCs) obtained from surgically resected cancer tissues.The analytical performance of our method showed a 92% concordance rate with DNA sequence analysis in detecting APC abnormalities." (PMID 39858085, 2025). "As a key player in regulatingcell cycle progression, APC/C isvery often misregulated in cancer." (PMID 40397069, 2025). "However, any mechanism/molecule that suppresses APC/C activity that is intended to be developed as a therapeutic agent to work in combination with current anti-cancer drugs must be developed under several strict restraints." (PMID 40650052, 2025). "In addition, an investigation using adenomatous polyposis coli-multiple intestinal neoplasia (APC Min/+) mice as a natural model of cancer pathology revealed another approach for assessing hypoxia." (PMID 41301888, 2025). "Therefore, as judged by the prolonged time cells spendin the metaphase, membrane-permeant EE2H6 targets APC/Cactivity and results in increased postmitotic cell death in a subsetof cancer cell lines." (PMID 40397069, 2025). "The dual-hit nature of APC inactivation (biallelic mutations) follows the Knudson model, where FAP patients harbor a germline mutation and develop polyps that, upon acquiring a second somatic hit, rapidly progress to carcinoma." (PMID 41228231, 2025). "Given lower b-catenin levels in serrated pathway CRCs compared to APC-mutant carcinomas, TCF4 overexpression could efficiently drive WNT activation in a manner that is favorable to these tumors." (PMID 40687798, 2025).
cancer (continued). "As APC has been previously identified as an RNA-binding protein that preferentially binds 3′ UTRs during mouse neurogenesis, our results suggest that APC promotes proximal poly(A) site use and that APC loss and altered expression contribute to pervasive APA dysregulation in cancers." (PMID 39375704, 2024). "Our results showed that human colon fibroblasts exposed from APC-EVs, but not from WT-EVs, exhibited the phenotypes of cancer-associated fibroblasts (CAFs) through EV-mediated NF-κB pathway activation." (PMID 39056778, 2024). "Together, this raises the question whether APC-driven nucleation activity choreographs invadopodia- or pseudopod-like (herein finger-like protrusions) dynamics to promote cancer invasion, alone and/or in concert with other actin nucleation factors." (PMID 38680662, 2024). "It is also plausible to assume that the MAPK-dependent APC/C inhibition pathway may contribute to the pathogenesis of multiple cancers." (PMID 39412391, 2024). "Genetic deletion of COX or PGE2 inhibits cancer in subcutaneous tumor models, and pharmacological inhibition using celecoxib was found to be a potent cancer-preventative measure in a mouse intestinal tumor model driven by mutant APC." (PMID 38870403, 2024). "Although mutations in APC are correlated to developing cancers after infection, a direct mechanism involving pathogen regulation of APC has never been described." (PMID 38562145, 2024). "For example, the APC/C:Cdc20 pathway is critical for the proper segregation of chromosomes during cell division, and its dysregulation can result in aneuploidy and chromosomal instability, which are common features of aggressive cancers." (PMID 39201599, 2024). "Therefore, when Pin1 is overexpressed and CDK is constitutively expressed, like in cancer cells, the G1/S regulatory checkpoint breaks down as the APC/CCDH1 is inhibited and the cell proliferates unchecked." (PMID 38727267, 2024). "One can investigate the ordered events in the DNA damage sensing and response in different cellular backgrounds including repair-deficient cells such as BRCA mutation or other cancer susceptibility states (ATM, mismatch repair, Fanconi, PTEN, Wnt/beta-catenin/APC, Rb, etc.)." (PMID 38709242, 2024). "CRAs harboring both APC and KRAS mutations may demonstrate a heightened predisposition toward carcinoma development." (PMID 39554798, 2024). "Yet, biallelic APC mutations have been previously associated with increased Wnt signaling and decreased T cell infiltration in both MSS and MSI‐H CRC tumors by us22 and in other cancer types." (PMID 36341526, 2023).